IL6 (interleukin 6)
Diseases named in the same sentence as IL6 in open-access papers (continued):
Sharing a sentence is not in itself a finding about the gene and the disease.
Insulin resistance (continued). "Chronically elevated levels of IL-6 contribute to insulin resistance and systemic inflammation, playing a role in the pathogenesis of T2DM." (PMID 40091956, 2025). "Correlation analyses between gut microbiota, immunoglobulins, and serum indicators revealed that genera, such as Anaerovibrio and Veillonella, positively correlated with IL-6 or insulin resistance suppressed in the PCA and EU group." (PMID 41227496, 2025). "Although leptin and adiponectin help regulate energy and metabolism, other variables such as TNF-α, IL-6, and resistin can worsen insulin resistance." (PMID 40002424, 2025). "Conversely, oxidative stress can damage adipose tissue, prompting the release of adipocytokines, such as TNF-α and IL-6, which induce inflammation and exacerbate insulin resistance." (PMID 40842498, 2025). "IL‐6's role in insulin resistance is exacerbated by its interaction with other cytokines like TNF‐alpha and IL‐8, which are elevated in adipocytes of insulin‐resistant individuals." (PMID 40551726, 2025). "A 12-week trial in 48 patients with Type 2 DM showed that vitamin D supplementation after 3 months reduced biochemical markers, IL-6, fasting insulin, and homeostatic model assessment for insulin resistance levels." (PMID 40041571, 2025). "Elevated levels of IL-6 and TNF-α are associated with chronic low-grade inflammation, contributing to insulin resistance, impaired glucose metabolism and increased cardiometabolic risk." (PMID 40362742, 2025). "Regarding the IL-6 marker, regression analysis demonstrated a strong positive correlation with the occurrence of hypertriglyceridemia and insulin resistance in both models." (PMID 40137151, 2025). "IFN-γ also promotes M1 macrophage polarization and enhances the expression of TNF-α and IL-6, thereby exacerbating systemic inflammation and insulin resistance." (PMID 40869401, 2025). "Supporting the observation of insulin resistance in KO mice, we found higher expression of inflammatory cytokines, including TNFα, IFNγ, IL-1β, IL-6 and IL-22, in the muscles of KO mice fed with normal diet, compared to the control mice." (PMID 41234234, 2025). "Systemic release of proinflammatory cytokines, particularly TNF-α and IL-6, induces insulin resistance, impairing glucose uptake by peripheral tissues and enhancing hepatic gluconeogenesis." (PMID 40615660, 2025). "In patients with rheumatoid arthritis, inflammatory cytokines (tumor necrosis factor-α and interleukin-6) and C-reactive protein have been shown to be positively correlated with the insulin resistance index (homeostasis model assessment)." (PMID 41464548, 2025). "TLR activation produces proinflammatory cytokines (TNF-α, IL-6, and IL-1β) that are essential in developing insulin resistance." (PMID 40076851, 2025). "Metformin, the cornerstone of diabetes treatment, alleviates the asthmatic burden by countering IL-6-mediated inflammation, oxidative stress, and insulin resistance." (PMID 41327676, 2025). "Adipokines are proinflammatory, such as TNF-α, IL-6, and resistin, which participate in inflammation and activation of other inflammatory pathways that lead to insulin resistance and metabolic diseases." (PMID 40013194, 2025). "This inflammatory state disrupts insulin signaling, with cytokines such as tumor necrosis factor‐alpha (TNF‐α) and interleukin 6 (IL‐6) leading to insulin resistance and complications such as type 2 diabetes." (PMID 40968498, 2025). "Compared to IL-6 and TNF-α, which also contribute to systemic inflammation in PCOS, IL-18 appears to have a stronger association with insulin resistance." (PMID 40385768, 2025). "Elevated levels of inflammatory markers such as IL-6, IL-17, and TNF-α are commonly observed in PCOS patients and are closely associated with follicular developmental arrest, insulin resistance, and metabolic syndrome." (PMID 41267865, 2025).
Insulin resistance (continued). "CRP, an acute-phase protein produced by the liver, promotes the inflammatory response by increasing the synthesis of TNF-α and IL-6, which in turn contributes to insulin resistance." (PMID 40842498, 2025). "IL-6 promotes insulin resistance by disrupting insulin signaling pathways and enhancing the inflammatory milieu, particularly through the activation of the JAK/STAT and NF-κB pathways." (PMID 40804870, 2025). "Insulin resistance leads to increased secretion of pro-inflammatory cytokines (e.g., IL-6, TNF-α), endothelial activation, and macrophage infiltration, all of which promote atherogenesis and plaque vulnerability." (PMID 40948866, 2025). "In skeletal muscle, IL-6 has been shown to induce insulin resistance (euglycemic–hyperinsulinemic clamps) possibly by an increase in intramuscular NEFA uptake, accumulation of NEFA-derived metabolites, and inhibition of glucose disposal." (PMID 39998445, 2025). "NF-κB is a key transcription factor involved in the production of pro-inflammatory cytokines such as TNF-α, IL-6, and IL-1β, which are elevated in conditions like obesity and insulin resistance." (PMID 40926269, 2025). "As a result, the risk of acquiring insulin resistance and T2D is higher in individuals with elevated circulating levels of pro-inflammatory mediators (CRP, IL-6, and IL-1β) and in obese individuals." (PMID 40566527, 2025). "H. pylori infection induces systemic inflammation through the release of pro-inflammatory cytokines such as TNF-α, IL-1, and IL-6, which disrupt insulin signaling pathways and exacerbate insulin resistance." (PMID 40551731, 2025). "Abnormal fat accumulation not only releases various inflammatory factors (e.g., tumor necrosis factor-α and interleukin-6) but also disrupts insulin signaling, further worsening insulin resistance." (PMID 39920728, 2025). "IL-6 produced by skeletal muscles reduces glucose production, improves insulin resistance and improves beta cell function and glucose homeostasis." (PMID 41011232, 2025). "IL-6 is a pro-inflammatory cytokine, and its levels are often elevated in response to chronic low-grade inflammation, contributing to insulin resistance and disease progression." (PMID 41011276, 2025). "Chronic elevations of IL-6 can induce insulin resistance in the liver by inhibiting glycogen synthase and activating glycogen phosphorylase thus increasing glycogenolysis and EGP, and in the adipose tissue by increasing lipolysis and NEFA production." (PMID 39998445, 2025). "Findings: Pro-inflammatory cytokines such as IL-1β, IL-6, and IL-17 contribute to islet inflammation, insulin resistance, and microvascular damage in both T1D and T2D." (PMID 40804870, 2025). "Inflammatory factors from adipose tissue (TNF-α, IL-6) disrupt insulin signaling, exacerbating lipid synthesis and insulin resistance." (PMID 40129589, 2025). "CRP, produced in response to cytokines such as interleukin-6 and tumor necrosis factor-α, reflects chronic low-grade inflammation that promotes insulin resistance, endothelial dysfunction, and dyslipidemia." (PMID 41301855, 2025). "Chronic systemic inflammation, mediated by cytokines, such as TNF-α, IL-6, and IL-17, plays a pivotal role in metabolic dysregulation, exacerbating insulin resistance, adipokine imbalance, and lipid dysfunction." (PMID 40137170, 2025). "Exposure to PM2.5 also raises levels of tumour necrosis factor-alpha, interleukin 6 (IL-6), resistin, and leptin, potentially contributing to insulin resistance and the onset of Type 2 DM." (PMID 40817200, 2025). "Research shows that IL-6 from fat tissue influences liver insulin resistance by increasing Suppressor of Cytokine Signaling 3 (SOCS3) levels." (PMID 40969371, 2025). "As shown in the insulin resistance pathway, expression of IL6 and IRS1 were upregulated, while INSR was downregulated in T2DM macaques." (PMID 40878918, 2025).
Insulin resistance (continued). "The chronic inflammation interferes with insulin signaling through cytokines, such as Tumor necrosis factor-α and Interleukin- 6(TNF-α and IL-6), and inhibits adipocyte differentiation, leading to insulin resistance and lipid accumulation." (PMID 41019065, 2025). "Research has shown that the activation of PPARγ can reduce the transfer of fatty acids to the liver, decrease insulin resistance, and inhibit the expression of IL-6 and TNF-α." (PMID 39064674, 2024). "It has been shown to reduce the levels of pro-inflammatory cytokines such as IL-1β, IL-6, and TNF-α, which are associated with insulin resistance and chronic inflammation in diabetes." (PMID 39092264, 2024). "It is known that insulin resistance of skeletal muscle is induced in T2D via increased ROS and inflammatory cytokines (IL-6, TNFα, etc.)." (PMID 38392186, 2024). "IL-6 levels predict the development of DM, and when administered peripherally in mice, Il-6 induces hyperglycemia, hyperlipidemia and insulin resistance by the downregulating of IRS and the upregulating of SOCS-3." (PMID 38339160, 2024). "Raspberry consumption did not have a significant effect on fasting blood glucose, insulin, hemoglobin A1C, glucose tolerance tests, homeostatic model assessment for insulin resistance, C-reactive protein, and interleukin-6 concentrations." (PMID 38860149, 2024). "We chose to investigate IL-6 due to its known effect on establishing insulin resistance and because it is considered a predictor of mortality in cardiorenal syndromes." (PMID 39596537, 2024). "Studies have described that chronic inflammation leads to the production of cytokines such as TNF-α and IL-6 that activate intracellular pathways, which lead to insulin resistance." (PMID 39590844, 2024). "Supplementing with omega-3 boosted IL-6 and beta-cell activity considerably while having little impact on other insulin resistance and glycemic measures." (PMID 39347373, 2024). "Inflammatory factors such as TNF-α, IL-6, and C-reactive protein are known to contribute to insulin resistance in GDM." (PMID 39759105, 2024). "Inflammatory cytokines, such as Tumor Necrosis Factor (TNF) α and IL-6, disrupt the insulin signaling pathways, exacerbating hepatic insulin resistance and promoting steatosis, liver injury, and fibrosis." (PMID 38999756, 2024). "CRP, another inflammatory mediator, is produced by both adipocytes and the liver in response to IL-6; circulating levels of hs-CRP are considered markers for cardiovascular disease risk and have been linked to insulin resistance." (PMID 39062848, 2024). "Interleukin-6 (IL-6) is a pro-inflammatory cytokine critical in diabetes pathophysiology, primarily through its roles in inflammation and insulin resistance." (PMID 39857603, 2024). "IL-6 is expressed in many inflammatory cells, regulating various biological processes, including inflammation and insulin resistance." (PMID 39275255, 2024). "High levels of inflammatory markers like C-reactive protein (CRP), interleukin-6 (IL-6), and tumour necrosis factor-alpha (TNF-α) are strong predictors of CVD risk and are also associated with insulin resistance and metabolic syndrome." (PMID 38999799, 2024). "Highly metabolically active visceral fat generates several pro-inflammatory adipokines, such as resistin, TNF-α, and IL-6, contributing to systemic inflammation, insulin resistance, and the onset of metabolic disorders." (PMID 39335642, 2024). "TNF-α and IL-6 are not only pivotal in the inflammatory response but also directly exacerbate metabolic dysfunctions, leading to insulin resistance and the advancement of atherosclerosis, thereby linking obesity directly with increased cardiovascular risk." (PMID 39064298, 2024). "It is an inhibitory cytokine that can attenuate the apoptosis of β-cells, suppression of insulin secretion, and peripheral insulin resistance induced by pro-inflammatory cytokines such as IL-6 and TNF-α." (PMID 39574905, 2024).
Insulin resistance (continued). "Pro-inflammatory markers, such as tumor necrosis factor α (TNF-α), interleukin-6 (IL-6), interleukin-1β (IL-1β), and leptin, demonstrate a positive correlation with insulin resistance and the characteristics of MetS." (PMID 38671898, 2024). "These senescent cells secrete senescence-associated secretory phenotypes (SASPs), such as activin A, IL-6 and TNF-alpha, that induce insulin resistance." (PMID 38937415, 2024). "The pathogenesis of metabolic syndrome is mainly mediated by increased free fatty acids leading to insulin resistance and chronic low-grade inflammation induced by pro-inflammatory cytokines such as IL-6, TMF-α, and leptin." (PMID 39139641, 2024). "Produced by adipose tissue, endothelial cells, and immune cells in response to hyperglycemia, IL-6 levels are elevated in diabetic patients, where they play a role in insulin resistance and chronic inflammation." (PMID 39857603, 2024). "As an important regulator of CRP, IL-6 induces insulin resistance and dyslipidemia, and is directly related to the consequences of vascular lesions." (PMID 40302954, 2024). "Although the role of IL-6 in insulin resistance is controversial, it has been targeted as a potential treatment for metabolic inflammation." (PMID 39606781, 2024). "Visceral adiposity resulting from insulin resistance led to an imbalance in the secretion of IL-6 and CRP inflammatory mediators." (PMID 39221158, 2024). "Upon exercise, myostatin decreases, and its expression has been correlated to a decrease in plasma levels of glucose, insulin, and IL-6 and a reduction in IR (calculated with the Homeostatic Model Assessment for Insulin Resistance Index, HOMA-IR)." (PMID 39337980, 2024). "The release of cytokines such as IL-6 promotes gluconeogenesis and insulin resistance, while elevated adrenocorticotropic hormone (ACTH) levels following trauma further exacerbate hyperglycemia by stimulating cortisol production." (PMID 39061646, 2024). "For example, a low dose of 30 μM DHA at physiological or nutritional levels ameliorated palmitate (500 μM)-induced insulin resistance and the expression of inflammatory genes (TNFα and IL-6) in C2C12 cells." (PMID 38501107, 2024). "Adipocytes in adipose tissue release IL-6 and IL-8 in obese individuals which induces insulin resistance particularly in hepatocytes and results in DM73." (PMID 38961103, 2024). "Excessive adipose tissue produces a number of proinflammatory cytokines, such as TNF-α, IL-6, and IL-1β, promoting local and systemic chronic low-grade inflammation and resulting in insulin resistance." (PMID 39125786, 2024). "Increased inflammatory cytokines levels released by adipose tissue, including TNF-α and IL-6, promote insulin resistance and correlate with the progression of diabetic nephropathy (DN)." (PMID 38510054, 2024). "Plasma IL-6, hsCRP, and leptin were positively correlated, whereas plasma adiponectin levels were negatively correlated to markers of adipose tissue insulin resistance." (PMID 38786765, 2024). "Chronic hyperglycemia and insulin resistance trigger systemic inflammation, leading to the release of pro-inflammatory cytokines, such as interleukin-6 (IL-6) and tumor necrosis factor-alpha (TNF-α)." (PMID 39728750, 2024). "Recent studies have shown that IL-6 has a significant relationship with insulin resistance, which plays an important role in the pathogenesis of PCO." (PMID 38368454, 2024). "High glucose levels can stimulate monocytes to enhance the synthesis and release of interleukin-6 (IL-6), and elevated serum IL-6 exacerbates insulin resistance, prompting the liver to release glucose and contributing to hyperglycemia." (PMID 38725059, 2024). "Chronic inflammation driven by cytokines (such as IL-17, TNFα, and IL-6) exacerbates insulin resistance, which plays a key role." (PMID 39598018, 2024).
Insulin resistance (continued). "IL-6 induces insulin resistance by reducing GLUT4 and IRS1 expression by activating the JAK-STAT (mediates cellular inflammatory response and cellular signals, such as insulin growth factor) and increasing SOCS3 expression." (PMID 38397916, 2024). "The increase in blood sugar can induce insulin resistance, leading to liver lipid metabolism disorder and low-grade systemic inflammation, increasing inflammatory mediators such as IL-6 and TNF-a in the plasma." (PMID 38596638, 2024). "Arecoline can also stimulate the production of pro-inflammatory cytokines, such as TNF-α and IL-6, which are known to lead to insulin resistance and MetS." (PMID 38894993, 2024). "Insulin resistance is also associated with increased levels of pro-inflammatory cytokines, TNF alpha and IL-6." (PMID 39457712, 2024). "This is an important finding as IL-6 is a pro-inflammatory cytokine that plays a role in insulin resistance." (PMID 38337640, 2024). "Currently, chronic inflammation mediated by cytokines (IL-17, TNFα, adiponectin, IL-6) is implied in the development of insulin resistance." (PMID 39598018, 2024). "After the investigation, body weight, fasting blood sugar (FBS), irisin, insulin, C‐reactive protein (CRP), interleukin‐6 (IL‐6), interleukin‐1 beta (IL‐1β), leptin, adiponectin, and insulin resistance (IR) were assessed." (PMID 39479712, 2024). "Nevertheless, prolonged stimulation of the IL-6 signaling during chronic systemic inflammation coincides with development of insulin resistance." (PMID 39723211, 2024). "Elevated levels of pro-inflammatory cytokines such as Interleukin-6 (IL-6) and tumor necrosis factor-alpha (TNF-α) are implicated in insulin resistance by disrupting the insulin signaling pathway." (PMID 39691364, 2024). "This is seen in adipocytes where kynurenine, another known endogenous AhR ligand, triggers STAT3/IL-6, leading to insulin resistance and in cancer cells where this pathway leads to tumor resistance." (PMID 39684781, 2024). "IL-6 disrupts insulin signaling by increasing the phosphorylation of insulin receptor substrates, thereby promoting insulin resistance." (PMID 39906735, 2024). "IL-6 is susceptible to production induced by TNF-α, which can worsen hepatic steatosis, insulin resistance, and inflammation in the pathogenesis of NAFLD, thereby facilitating the onset and progression of the disorder." (PMID 39161898, 2024). "MetS induces chronic low-level inflammation with a constant increase in TNF-α and IL-6 cytokines, especially among obese individuals, and develops insulin resistance and TG circulation." (PMID 38785834, 2024). "First, the elevated levels of TNF‐α and IL‐6 in the presence of CRC can lead to insulin resistance, making it harder for muscle cells to utilize glucose effectively." (PMID 38924332, 2024). "These substances include adiponectin, leptin, IL-1, IL-6, IL-10, angiotensinogen, chemokines, serum amyloid protein, and many more, which can contribute to the worsening of insulin resistance and T2DM." (PMID 39328924, 2024). "IL-6 has been demonstrated to induce insulin resistance by impairing the phosphorylation of the insulin receptor and insulin receptor substrate-1." (PMID 39519203, 2024). "The modulation of inflammatory markers like interleukin-1β (IL-1β), tumor necrosis factor-α (TNF-α), and interleukin-6 (IL-6) is crucial in T2DM, as their elevated levels are associated with disease progression, insulin resistance, and β-cell dysfunction." (PMID 39840100, 2024). "The elevation of pro-inflammatory mediators, such as IL-6 and TNFα, is believed to contribute to the onset of various age-related conditions, including diabetes mellitus and insulin resistance." (PMID 38317257, 2024). "Several studies have confirmed that central IL-6 activation can prevent high-fat-diet-induced obesity and insulin resistance in mice." (PMID 39749325, 2024).